IL6 (interleukin 6)
Diseases named in the same sentence as IL6 in open-access papers (continued):
Sharing a sentence is not in itself a finding about the gene and the disease.
depression (continued). "In depression animal models, studies found that restraint stress stimulated the increased levels of IL-6, and administration of LPS or recombinant IL-6 induced depressive-like behaviors." (PMID 34421539, 2021). "Furthermore, tumor necrosis factor-α (TNF- α), interleukin-1β (IL-1β), and interleukin-6 (IL-6) measured in the cerebrospinal fluid of MS patients correlate with depression scores." (PMID 34764926, 2021). "Clinical studies have indicated that patients suffering from depression showed significantly higher levels of proinflammatory cytokines, including interleukin-1β (IL-1β), interleukin-6 (IL-6), tumor necrosis factor alpha (TNF-α), C-reactive protein (CRP), and inflammasome, than healthy people." (PMID 33466877, 2021). "Furthermore, central and peripheral pro-inflammatory cytokines; tumor necrosis factor-alpha (TNF-α), interleukin-6 (IL-6), and interleukin 1β (IL-1β) were reported to have a strong correlation with depression." (PMID 34804417, 2021). "In this study, we could only focus on some candidates of the inflammatory system, which might be linked to catecholamines, depression and CAD, i.e., IL-6 and MCP-1." (PMID 33801190, 2021). "For example, chronic light deprivation also induces IL-6-dependent depression-like behavior through activation of nuclear factor-κB (NF-κB) signaling and may be associated with seasonal affective disorder marked by depressive symptoms." (PMID 34531719, 2021). "Patients with higher IL-6 at baseline showed worse depression scores at 2 years." (PMID 34712729, 2021). "As well as IL-6, IL-1β is one factor with notable implication in the pathophysiology of depression." (PMID 34358084, 2021). "Data supporting the role of inflammation in depression are extensive: depression is associated with increased inflammatory biomarkers like elevated CRP and Interleukin 6 (IL-6), and a pro-inflammatory state might worsen the outcome of depression." (PMID 33801190, 2021). "Probiotic Lactobacillus plantarum has demonstrated an anti-depressive effect in mice models and adults with depression and is involved in the mitigation of inflammation through downregulation of IL-6 and TNF-α and significant restoration of intestinal permeability and Lactobacillus population." (PMID 34065187, 2021). "A longitudinal cross-lagged twin study has provided compelling evidence supporting the imperative role of IL-6 increase as an independent risk factor of depression rather than an epiphenomenal consequence of disease’s establishment." (PMID 34367160, 2021). "In addition, although observational studies have consistently reported elevated CRP and IL-6 levels in depression and schizophrenia, MR analysis has reported a protective effect of CRP for schizophrenia." (PMID 33684738, 2021). "Still, recently, it was demonstrated that the inhibition of IL-6 could contribute to the worsening of depressive disorders which are more prevalent in the elderly population and, even more so, in the elderly population with some neurodegenerative disease." (PMID 33918172, 2021). "However, another study found that the relationship between depression and IL-6 levels were observed in patients on continuous ambulatory peritoneal dialysis, but not in HD patients." (PMID 32235786, 2020). "Among the common functional IL6 genetic variants, some studies demonstrated that the IL6 rs1800795 C allele increased the risk for depression, however not by all." (PMID 32235786, 2020). "In a study, IL-6 knockout mice became resistant to the development of depression-like symptoms." (PMID 32714875, 2020). "Elevated pro-inflammatory markers, especially interleukin-1, interleukin-6 and tumour necrosis factor-alpha are seen in patients with depression and we already know that inflammation may induce depression." (PMID 33176747, 2020). "IL-6, CRP and triglycerides are likely to be causally linked with depression, so could be targets for treatment and prevention of depression." (PMID 30886334, 2020).
depression (continued). "Additionally, serum IL-6 and IL-1Ra, also known to be produced by M1 macrophages, were shown to be significantly higher in major depression patients as well as in patients resistant to treatment compared to healthy controls." (PMID 32380663, 2020). "Results demonstrated that changes in depression severity were associated with incremental changes in blood levels of S100B, but not IL-6." (PMID 32235786, 2020). "Moreover, serum IL-6 is considered a predictive biomarker for ketamine’s antidepressant effect in treatment-resistant patients with depression." (PMID 32522211, 2020). "Furthermore, IL-6 knockout mice exhibit resistance to stress-induced depression-like behaviors, suggesting that IL-6 plays a key role in eliciting depression." (PMID 32367035, 2020). "Inflammasome activation and expression of proinflammatory cytokines, such as IL-1β, IL-6, and IL-18, due to dysbiosis state, may be related to major depressive disorders." (PMID 33105830, 2020). "In addition, in our reserpine-induced animal model of depression, levels of IL-1β, IL-6, and TNF-α were significantly higher than those in control mice." (PMID 32754030, 2020). "Both IL-6 and IL-1β are important in the pathophysiology of major depression." (PMID 33029297, 2020). "The improvement in depression correlated with normalization of pro-inflammatory biomarkers, including pro-inflammatory adipokines (leptin) or cytokine (IL-6), suggests a role for inflammatory pathways and intriguing links between PPARγ activation, depression, and inflammation." (PMID 32971941, 2020). "Certain risk factors for CHD, specifically IL-6, CRP and triglycerides, are likely to be causally linked with depression, so these could be targets for treatment and prevention of the illness." (PMID 30886334, 2020). "In summary, our results suggested that MT, IL-6, hcy, and complement factor C3 may be of great importance in pathogenesis process of depression." (PMID 32655450, 2020). "In these studies, depression is associated at it's peak with high levels of general inflammation markers such as C-reactive protein (CRP) as well as high levels of pro-inflammatory cytokines such as tumor necrosis factor alpha (TNFα) and interleukin 6 (IL6)." (PMID 33240126, 2020). "The study found that the vegetative symptoms, such as appetite loss, insomnia and fatigue, but not depression symptoms, were significantly associated with IL-6 levels." (PMID 32235786, 2020). "Another review noted that vitamin D supplementation can robustly reduce TNF-α and IL-6, but not other cytokines, yet TNF-α and IL-6 were the two cytokines that were the most robustly associated with depression in a meta-analysis." (PMID 32629761, 2020). "Moreover, accumulating evidence from rodent and human studies suggests that IL-6 mediates the communication between peripheral and central nervous system, thereby playing a key role in the pathophysiology of depression." (PMID 32655424, 2020). "Several studies have investigated whether peripheral IL-6 levels are significantly higher in the elderly with depression." (PMID 32235786, 2020). "Another study found a correlation of IL-6 levels with both depression and fatigue in HD patients." (PMID 32235786, 2020). "While such IL-6-action may be related to some other psychiatric disorders like unipolar depression, elevation of cortisol production by IL-6-action could also be linked to schizophrenia." (PMID 32061259, 2020). "We found the evidence for an association of current depression with raised CRP and raised triglycerides, which is consistent with our recent MR study reporting that triglycerides, as well as IL-6 and CRP, could be causally linked to depression." (PMID 32339985, 2020). "Moreover, abnormally high levels of pro-inflammatory cytokines, such as interleukin 6 (IL-6), can be found in depressed patients, which is why theories link depression to inflammation." (PMID 32296353, 2020).
depression (continued). "This fact has been further supported by various studies wherein higher concentrations of pro-inflammatory cytokines (such as IL-1β and IL-6) and low concentrations of anti-inflammatory cytokines (like IL-4 and IL-10) were detected in patients enduring with depression." (PMID 33415126, 2020). "In addition, Mendelian randomization studies support potential causal associations between IL-6, CRP and depression." (PMID 32755646, 2020). "The mechanism of the relationship between depression and pancreatic cancer is still poorly understood; however, one of the widely considered theories describes the increased levels of IL-6, among other inflammatory cytokines, as the link to major depression preceding the cancer diagnosis." (PMID 32850269, 2020). "The association between log IL-6 and TS total score became non-significant (r = 0.01, N = 62, p>0.05) in those without depression." (PMID 32413063, 2020). "Specifically, MDD is accompanied by immune dysregulation, resulting in increased production of proinflammatory cytokines (e.g., interleukin (IL)-6 and tumor necrosis factor (TNF)-α), which could lead to depression-linked abnormalities in brain function." (PMID 32230840, 2020). "Additionally, it has been shown that IL-6 induces the production of inflammatory T helper 17 cells (Th17), thus increasing levels of these cells in the brain during depression-like states." (PMID 32188010, 2020). "Similar sex-specific findings were reported for healthy subjects given a peripheral immune challenge; females experienced more depression-related symptoms, and there was a positive correlation of pro-inflammatory interleukin-6 (IL-6) levels and depression-related symptoms only in females." (PMID 32066699, 2020). "A study in a Hungarian population sample of 1053 volunteers found that this functional IL6 rs1800795 polymorphism interacted with the recent negative life events to increase the risk of depression." (PMID 32235786, 2020). "IL-6 has also been correlated to pancreatic cancer comorbidities, such as cachexia and depression." (PMID 32850269, 2020). "The pro-inflammatory cytokine IL-6 was also increased in participants with depression." (PMID 32528052, 2020). "IL-1β and IL-6 have been shown to be increased in some brain regions of patients with depression." (PMID 32321532, 2020). "However, there are conflicting views on the influence of IL-6 on STAT3 in the regulation of depression as well as glucose homeostasis." (PMID 32655424, 2020). "In the course of depression in elderly people (>65 years of age), a decreased level of methylation of interleukin 6 gene (IL-6), which significantly increases as a result of antidepressant treatment, may be of importance." (PMID 32373361, 2020). "When laboratory measures of inflammation were explored, there was a trend toward anxiety (but not depression) being associated with increased stimulated IL‐6 levels for healthy adolescent controls." (PMID 31199593, 2020). "Certain serotonin re-uptake inhibitors may alleviate depression, in part because of their effects on cytokines such as interleukin-6 (IL-6) and tumour necrosis factor (TNF)-α, whereas other antidepressants do not appear to reduce cytokine levels." (PMID 31996235, 2020). "The up-regulation of IL-6 has been reported in different neuroinflammatory and neurodegenerative disorders of the central nervous system, pulmonary hypertension, metabolic syndrome, depression as well as cancer." (PMID 31991717, 2020). "In addition, various studies demonstrated increased serum levels of TNF-α, IL-1β, and IL-6 in patients with depression." (PMID 32184729, 2020). "In this review, we focus on the role of IL-6 in depressive disorder from various aspects." (PMID 32235786, 2020). "It should be noted that several factors such as high body mass index (BMI), smoking and physical comorbidity may affect IL-6 levels, and people with depressive disorders frequently exhibit these lifestyle factors." (PMID 32235786, 2020).
depression (continued). "Depressive disorders is characterized by inflammation, as indicated by elevated concentrations of pro-inflammatory cytokines (e.g., IL-1β, IL-2, and IL-6), and it is characterized by cell-mediated immune (CMI) activation and Th1-like response, as suggested by increased production of IFN-γ." (PMID 31215856, 2020). "Among these pro-inflammatory cytokines, animal studies and clinical studies had demonstrated that IL-6 may have a special role in the pathogenesis and somatic consequences of depressive disorder, as well as in the effects of depressive disorder treatment." (PMID 32235786, 2020). "Pectin can improve depression, which may be due to the influence of IL-6 concentration and JAK–STAT signaling pathway in hippocampus of mice." (PMID 31491962, 2019). "Moreover, in contrast to the situation in depression, the evidence that interleukin-6 (IL6) levels are increased in patients with ASD is extremely sparse." (PMID 30813406, 2019). "The proinflammatory mediators, TNF-α and IL-6, were related to the etiologies of depression." (PMID 30823679, 2019). "Consistently, in our previous study, administration with nesfatin-1 could induce depression-like behaviors, accompanied with the increased plasma concentrations of IL-6 and CRP." (PMID 32009956, 2019). "Meta-analytic results have shown significantly higher concentrations of the pro-inflammatory cytokines TNF-α and IL-6 in depressed subjects compared with control subjects, strengthening the evidence that depression is accompanied by activation of the inflammatory response system." (PMID 31039822, 2019). "Indeed, IL-6 is consistently reported as elevated in the blood of patients with depression and has been proposed as a predictive biomarker." (PMID 31849598, 2019). "High plasma levels of IL-6 were associated with increased suicidal ideation and suicide attempts, and they were independent of depression severity." (PMID 31362361, 2019). "Recent evidence suggests that stress hormones may actually facilitate inflammation followed by depression, through induction of various cytokines including IL-1, IL-6, IL-8, IL-18 and TNF (tumor necrosis factor)." (PMID 31150403, 2019). "Correlations between circulating IL-6 levels and depression-like behavior have been previously observed when categorizing socially-defeated animals into susceptible and resilient groups, but our data suggest individual differences display more as a spectrum as opposed to two separate entities." (PMID 31139062, 2019). "However, this latter study reported that depressive symptoms during pregnancy, as well as the IL6 and IL-10 biomarkers, were significant predictors of postpartum Edinburgh Perinatal Depression Scale (EPDS) score." (PMID 30943938, 2019). "In addition, a recent study found a positive correlation between plasma IL-6 levels and depression severity in patients with CFS." (PMID 31253154, 2019). "For this reason, researchers have proposed that targeting peripheral IL-6 may be a potential treatment approach in depression." (PMID 31214060, 2019). "Taken together, the available evidence indicates that acute psychological stressors, likely through catecholaminergic signaling, as well as chronic stress and depression can give rise to increased circulating concentrations of IL-6, which is often presented as a marker of systemic inflammation." (PMID 30769887, 2019). "The present study suggests that increased serum IL-6 level might be a contributing factor to the pathogenesis of depression." (PMID 30899619, 2019). "Some of the inflammatory markers are considered as to be (potentially) significant for depression, e.g., the pro-inflammatory cytokines as interleukin-6 (IL-6), interleukin-1 (IL-1), and tumor necrosis factor (TNF-α), as well as the acute phase reactant protein C-reactive protein (CRP)." (PMID 31591316, 2019).
depression (continued). "Furthermore, elevated serum levels of several pro-inflammatory cytokines, such as TNFα, IL-1β, and IL-6, have also been detected in patients with depression." (PMID 31312123, 2019). "Increased serum concentrations of IL-6 were found in patients suffering from major depression." (PMID 30899619, 2019). "In addition to tocilizumab, sirukumab, another monoclonal antibody to IL-6, has also been proposed as a potential treatment for depression." (PMID 31214060, 2019). "Conversely, inflammation markers such as IL-6 are often elevated in depression." (PMID 31362361, 2019). "In addition, further evidence is provided by other studies showing that higher IL-6 levels predict future development of clinical depression." (PMID 31379879, 2019). "Because the etiology of depression is increasingly recognized as immune activation through secretion of proinflammatory cytokines, such as IL-1, IL-6, TNF-α, IFN-γ, leukotrienes, and prostaglandins, anti-neuroinflammatory activity has been proposed by many as a potential treatment for depression." (PMID 31251788, 2019). "Furthermore, inflammatory markers such as CRP, IL-6, and TNF-α have been associated with development or severity of psychiatric disorders such as depression, psychosis, and bipolar disorder." (PMID 31170007, 2019). "Increased circulating IL-6 was also observed in humans suffering from major depression." (PMID 31057357, 2019). "Ham-D: Hamilton Depression Rating Scale; IL-6: Interleukin-6; CRP: C-reactive protein; N: Number." (PMID 30899619, 2019). "Because higher levels of IL-6 are found in the CSF than in the blood and in patients with depression than in controls, IL-6 in the CSF was hypothesized to be the most promising therapeutic target." (PMID 31214060, 2019). "Increases in IL-6 levels have been demonstrated to be positively associated with negative AB only in response to typhoid vaccine in women with partially remitted depression, but not in response to laboratory stress or both treatments." (PMID 31068783, 2019). "Increasing evidence have supported a cytokine hypothesis of depression and the existence of a pro- inflammatory state in patients with unipolar depression (increased serum interleukin IL-6) and bipolar depression (increased levels of IL-1, IL-6 and TNF-α)." (PMID 31671812, 2019). "In depressed mice, the IL-6 release also correlated positively with the severity of depression." (PMID 32009871, 2019). "However, the trigger effects of IL-6 and IL-18 on depression were attenuated in patients receiving statins, suggesting that the antidepressant effects of such drugs are attributable to reductions in the actions of pro-inflammatory cytokines." (PMID 30890971, 2019). "Secondary analysis of existing RCTs suggests mAb against specific inflammatory cytokines, such as IL-6/IL-6R, could be helpful for depression." (PMID 31258105, 2019). "Our study findings provided additional evidence that significantly altered IL-6 activity may be involved to the pathophysiology of depressive disorder." (PMID 30899619, 2019). "Here we test the efficacy of BDPP and two novel phytochemicals derived from post-absorptive and microbiome metabolism of BDPP in attenuating depression by reversing stress-mediated brain synaptic maladaptation through modulation of peripheral IL-6 and Rac1 in the NAc." (PMID 29396460, 2018). "Furthermore, IL-6 concentration correlated with active depression in the primary depression patients." (PMID 30148175, 2018). "IL-4, IL-6, and IL-12 may change in bipolar disorder (BD) patients under different mood episodes (mania or depression episode)." (PMID 30170608, 2018). "Results from genetic association analysis informed by Mendelian randomisation (MR) indicate residual confounding is unlikely to explain the association between IL-6 and depression fully." (PMID 30244217, 2018).